SPAG7 (sperm associated antigen 7)
Synonyms: FSA-1; ACRP; MGC20134
Tractability: PROTAC: ubiquitination databases record sites on it; its protein half-life has been measured.
Gene: Protein-coding gene on chromosome 17 (4,959,226 to 4,967,825, reverse strand). Ensembl gene ENSG00000091640.
Subcellular location: Nucleus
Subcellular location (Human Protein Atlas): Nucleoplasm
Gene Ontology:
Molecular function: protein binding; nucleic acid binding
Cellular component: nucleoplasm; nucleus
Genetic constraint (gnomAD): Loss-of-function variants: 20 observed, 31.73 expected, observed/expected ratio (o/e) 0.63, 90% interval 0.44 to 0.92. The upper end of that interval is the gene's LOEUF score, 0.92, which puts it in group 3 of 6, group 1 being the genes least tolerant of losing a copy. Missense variants: 276 observed, 305.57 expected, observed/expected ratio (o/e) 0.9, 90% interval 0.82 to 1. Synonymous variants: 127 observed, 110.44 expected, observed/expected ratio (o/e) 1.15, 90% interval 1 to 1.33.
Homologues: Orthologues: chimpanzee SPAG7 (99% identical), mouse Spag7 (97% identical), guinea pig SPAG7 (96% identical), rat Spag7 (96% identical), tropical clawed frog spag7 (79% identical), pig SPAG7 (79% identical), dog SPAG7 (78% identical), zebrafish spag7 (74% identical), macaque SPAG7 (70% identical), Drosophila melanogaster CG2608 (37% identical).
Diseases named in the same sentence as SPAG7 in open-access papers:
SPAG7 is named in the same sentence as 10 diseases in open-access papers, as found by Europe PMC text mining. Sharing a sentence is not in itself a finding about the gene and the disease. The quoted sentences say what the papers report.
Insulin resistance (2 papers, 2024). Increased resistance towards insulin, that is, diminished effectiveness of insulin in reducing blood glucose levels. "The results show that SPAG7-deficient mice were born with lower body weight; however, they developed obesity and insulin resistance in adulthood." (PMID 39056292, 2024). "The surviving SPAG7 KO mice develop a range of metabolic disorders including obesity, insulin resistance, glucose intolerance, exercise impairment, reduced energy expenditure, and reduced skeletal muscle mitochondrial oxidative capacity in adulthood." (PMID 39056292, 2024). "Lack of SPAG7 results in IUGR, which leads to the development of obesity, insulin resistance, and other metabolic disturbances later in life." (PMID 39056292, 2024).
intrauterine growth restriction (2 papers, 2024). "At e18.5, SPAG7-deficient animals display decreased fetal and placental weight, indicating intrauterine growth restriction (IUGR)." (PMID 39056292, 2024). "Furthermore, SPAG7-deficiency in developing embryos leads to intrauterine growth restriction, brought on by placental insufficiency, likely due to abnormal development of the placental junctional zone." (PMID 39056292, 2024). "Furthermore, SPAG7 KO embryos display intrauterine growth restriction (IUGR), and aberrant development of the junctional zone of SPAG7-deficient placenta." (PMID 39056292, 2024).
Obesity (2 papers, 2024). Accumulation of substantial excess body fat. "From a forward mutagenetic screen to discover mutations associated with obesity, we identified mutations in the Spag7 gene linked to metabolic dysfunction in mice." (PMID 39056292, 2024). "The authors found that SPAG7-deficient mice were born underweight but developed obesity later in life and identified reduced energy expenditure as a key driver for the onset of obesity and metabolic syndrome in these mice." (PMID 39045266, 2024). "Further investigation of SPAG7-deficient mice may provide valuable information for drugs targeting energy expenditure in the treatment of obesity." (PMID 39056292, 2024). "Here, we show that SPAG7 KO mice are born smaller and develop obesity and glucose intolerance in adulthood." (PMID 39056292, 2024). "The key driver for the development of obesity and metabolic syndrome in the SPAG7 KO mouse is reduced energy expenditure." (PMID 39056292, 2024). "We hypothesize that a ‘thrifty phenotype’ is ingrained in SPAG7 KO animals during development that leads to adult obesity." (PMID 39056292, 2024).
Infertility (1 paper, 2023). "The miRNA-target gene interaction causes down-regulation of the SPAG7 gene, which may be associated with infertility." (PMID 36871032, 2023). "In this study, we aimed to identify the post-transcriptional regulation of SPAG7 in seminal plasma (SF-Native) and seminal plasma-derived extracellular vesicles (SF-EVs) collected from 87 men undergoing infertility treatment." (PMID 36871032, 2023). "Here, the expression levels of miR-15a-5p, miR-15b-5p, miR-16-5p, miR-195-5p, miR-424-5p, miR-497-5p, miR-6838-5p and that of SPAG7 mRNA were determined in both, in SF-EVs and SF-Native samples, collected from men undergoing infertility treatment." (PMID 36871032, 2023).
placental insufficiency (1 paper, 2024). Failure of the placenta to deliver an adequate supply of nutrients and oxygen to the fetus. "Deeper understanding of the mechanisms involved in placental insufficiency, IUGR, and SPAG7 biology may give us the opportunity to reverse aberrations in fetal growth rate and prevent the metabolic co-morbidities associated with low birth weight." (PMID 39056292, 2024).
cancer (2 papers, 2020 to 2025). A tumor composed of atypical neoplastic, often pleomorphic cells that invade other tissues. "Exactly, previous studies have shown that PRPF8, SPAG7, SENP3 and GPS2 are associated with the occurrence of various cancers." (PMID 40015977, 2025). "The fusion present in SPAG7 with higher stability than a reference transcript may also be important to understand because it is a cancer-testis (CT) antigen responsible for anticancer immune response activation." (PMID 32922662, 2020).
SPAG7 also shares sentences with these, for which no sentence is quoted: Glucose intolerance (1 paper); metabolic disorders (1); metabolic syndrome (1); pharyngitis (1).